TF (transferrin)
Diseases named in the same sentence as TF in open-access papers (continued):
Sharing a sentence is not in itself a finding about the gene and the disease.
thalassemia (30 papers, 2009 to 2026). An inherited blood disorder characterized by a decreased synthesis of one of the polypeptide chains that form hemoglobin. "Adult transfusion-dependentbeta-thalassemia patients; correlationof transferrin saturation and serumferritin with bone mass density." (PMID 41281279, 2025). "A recent study shows a higher level of ineffective erythropoiesis with high serum ferritin and transferrin saturation levels in newly diagnosed thalassemia patients." (PMID 40421055, 2025). "Quercetin reduced iron, ferritin, transferrin saturation, and high sensitivity C-reactive protein while it increased transferrin, which makes it a potent agent in improving the iron status in thalassemia." (PMID 38004496, 2023). "The sample collection methodology limited our ability to perform direct measurements of iron, ferritin, transferrin saturation, or genetic testing for thalassemia." (PMID 34335794, 2021). "Non-transferrin-bound iron is well documented in iron overloaded diseases like thalassaemia, where transferrin is fully saturated with iron." (PMID 32751493, 2020). "Nontransferrin-bound iron found in plasma is also well documented in iron overloaded diseases like thalassaemia, where transferrin is fully saturated with iron." (PMID 32486511, 2020). "In thalassemia, the increase in iron levels in the circulation exceeds the binding capacity of apotransferrin resulting in the presence of non-transferrin bound iron (NTBI)." (PMID 32219031, 2020). "Apart from this discrepancy on spleen iron, every other aspect of iron distribution in this proposed thalassemia treatment with transferrin injections is replicated in the model." (PMID 30608934, 2019). "The simulation suggests that the most important qualitative change between thalassemia minor and major is the full saturation of transferrin, leading to a complete dysregulation of iron homeostasis with extremely high NTBI levels and very low hepcidin." (PMID 30608934, 2019). "The heme by-product is transported to the liver by transferrin which in thalassemia can become saturated preventing removal." (PMID 28240317, 2017). "Non-transferrin-bound iron was high in the thalassemia and MDS groups but low in the SCA group (P<0.001)." (PMID 28257476, 2017). "Eighty thalassemia major patients were studied with respect to liver enzymes, ferritin, transferrin saturation, HBsAg, anti-HCV antibody and HCV-PCR for anti-HCV positive patients." (PMID 27275237, 2015). "In women with thalassemia, iron overload leads to accumulation of non-transferrin-bound iron (NTBI) in ovarian tissues, which generates reactive oxygen species (ROS) via the Fenton reaction, inducing oxidative stress and damaging ovarian cells, potentially impairing oocyte developmental potential." (PMID 41607608, 2026). "This is because it is believed that patients with thalassemia have increased plasma malondialdehyde and circulating non-transferrin bound iron (NTBI) relative to patients with SCD, and lower levels of some cytokines (interleukin 5 and interleukin 10) and γ-tocopherol." (PMID 34760898, 2021). "The model was also used to show how it could have a role in planning interventions (transferrin treatment in thalassemia)." (PMID 30608934, 2019). "The application of the model to simulate transferrin treatment in thalassemia provides an example of how such a model could eventually be used to plan and optimize therapies and interventions." (PMID 30608934, 2019). "Interestingly, despite a mean time on chronic transfusion of 4.1±2.4 years, mean transferrin saturation was 47.2%±23.6%, i.e., lower than the value expected after a comparable transfusion time in patients with thalassemia." (PMID 28257476, 2017). "Such a situation might be of importance in diseases such as thalassemia, where there is an abundance of iron-loaded transferrin in circulation." (PMID 25476866, 2015).
thalassemia (continued). "Low serum ferritin and transferrin saturation indicate IDA, while normal or elevated ferritin levels with microcytosis suggest thalassemia trait." (PMID 39674920, 2025). "Recent studies have shown the importance of other markers such as non-transferrin bound iron (NTBI) and labile plasma iron (LPI) to detect iron excess in thalassemia patients due to the direct correlation of these markers with the formation of free radicals." (PMID 26527217, 2015). "Apo-transferrin (apo-Tf), hepcidin agonists, JAK2 inhibitors, Tmprsso inhibitors, and activin receptor II (ActRII) ligand traps hold promise for improving iron overload management, averting splenomegaly and thrombosis, and decreasing the need for transfusions in individuals with ß-thalassemia." (PMID 39449307, 2024). "A previous study found that heart disease was not present in patients with thalassemia major and intermedia who showed negative plasma NTBI and had a plasma transferrin saturation of less than 70%8." (PMID 28287621, 2017). "To investigate this hypothesis, we examined the relationships between transferrin saturation and MCHC with each of the parameters that define MCHC in sickle patients (HbSS without α-thalassemia) and healthy volunteers (HVs)." (PMID 39659429, 2024).
leukemia (29 papers, 2014 to 2025). A malignant (clonal) hematologic disorder, involving hematopoietic stem cells and characterized by the presence of primitive or atypical myeloid or lymphoid cells in the bone marrow and the blood. "In MDS patients, a transferrin saturation > 80% and ferritin levels > 800 μg/L were associated with a poor 5-year OS, progression-free survival, and leukemia-free survival." (PMID 40635108, 2025). "Transferrin-independent iron is also associated with iron overload in leukemia." (PMID 31519186, 2019). "Few reports suggested that plasma levels of FVIIa-AT directly correlated with TF mRNA expression in leukemia cells." (PMID 38282902, 2024). "Transcription dysregulation is one of the key aberrations in pediatric leukemia given that ancestral fusions in tumor cells usually involve core TF genes in hematopoiesis." (PMID 37880218, 2023). "A recent study identified a critical role for ZFP64 as a TF (transcriptional factor) with an important role in maintaining the expression of the MLL oncogene in MLL (mixed lineage leukemia gene-rearranged leukemia)." (PMID 34996504, 2022). "IKZF1 is an important TF for the development of lymphocytes and has previously been connected to leukemia and autoimmune diseases." (PMID 36699378, 2022). "To further validate the specific CRC signature of KMT2Ar leukemia, we analyzed patterns of TF expression in BeatAML, a large data set of 510 genetically annotated and mRNA-sequenced primary AMLs." (PMID 35301220, 2022). "The research team mainly used transferrin-conjugated anionic lipid polymers to construct composite nano-drugs for the treatment of leukemia, which carried a mimic of microRNA-29b." (PMID 36299285, 2022). "It has been shown that activation of PC in an EPCR-dependent mechanism leads to inhibition of TF expression on U937 leukemia cell lines." (PMID 33947134, 2021). "For example, artesunate can induce ferroptosis in Adriamycin-resistant leukaemia cells by decreasing TF levels and promoting the therapeutic effect of Adriamycin on leukaemia." (PMID 34912804, 2021). "In this study, we have employed transferrin which will bind specifically to the transferrin receptor which is overexpressed in leukemia cells." (PMID 30191515, 2018). "Overall, transferrin-decorated paclitaxel-loaded lipid nanoparticle was prepared with an aim to increase the chemotherapeutic efficacy in the leukemia cells." (PMID 30191515, 2018). "In this study, transferrin-decorated paclitaxel-loaded lipid nanoparticle (TPLN) was prepared with an aim to increase the chemotherapeutic efficacy in the leukemia cells." (PMID 30191515, 2018). "In addition, leukemia cells are more likely to express transferrin and contain more iron than other tumor cells, which makes it easier for ROS to accumulate in leukemia cells and trigger ferroptosis." (PMID 38594732, 2024). "Thus, the core TF expression signature of KMT2Ar leukemia in this independent patient cohort largely matched the superenhancer and gene dependency signatures of KMT2Ar AML." (PMID 35301220, 2022). "Likewise, Zfp532 was found to be upregulated both in DF and TFD but not in TF mutants, suggesting that differential upregulation of zinc finger protein genes in TF- and DF-driven leukemias." (PMID 36073548, 2022). "We therefore explored whether MitMAB affects endocytosis in the leukemia cells, as determined by uptake of fluorescent transferrin." (PMID 34492077, 2021). "In addition, to compare the cellular effect of hRTL, K562 leukemia cells and HeLa cervical cancer cells were selected for the experiments, which express the β-galactoside-containing glycans and moderately express the TF-antigen." (PMID 39330281, 2024). "Other studies implicated MYC, a well-characterized TF with strong oncogenic potential, in the transcriptional regulation of CD47 during the progression of leukemia using MYC-induced T cell acute lymphoblastic leukemia mouse model; MYC T-ALL, and human leukemia cells lines; CCRF-CEM and Jurkat." (PMID 39742254, 2024).
leukemia (continued). "To more specifically assess if the observed leukemia-associated phenotype seen in TF, DF, and TFD mice is transplantable — and, if transplantable, how rapidly the disease manifests — we transplanted BM cells from WT, TF, DF, and TFD mice into lethally irradiated C57BL/6 host." (PMID 36073548, 2022). "We independently confirmed the selective dependency of KMT2Ar leukemia on IRF8 and MEF2D by measuring cell viability after CRISPR–Cas9 TF knockout in a panel of six cell lines." (PMID 35301220, 2022). "We first assessed the frequency of leukemia stem cell (LSC) containing LSK population and found this to be elevated in TF and TFD mice relative to WT controls." (PMID 36073548, 2022). "Our unsupervised clustering analysis showed that cases of leukemia driven by TF and TFD are more alike compared with leukemia driven by DF mutants." (PMID 36073548, 2022). "Recently, ZFP64 was identified to be a crucial TF in MLL-rearranged leukemia by controlling the expression of the oncogene MLL, prompting the formal proposal that ZFP64 was an important TF in cancer progression." (PMID 34996504, 2022). "Quantitatively, either one of the zinc finger protein genes was upregulated in TF and DF, while both Zfp521 and Zfp532 were uniquely upregulated in TFD HSC/Ps, possibly contributing to aggressiveness of TFD-driven leukemia." (PMID 36073548, 2022). "Transferrin was chosen to target RPMI8226 multiple myeloma and K562 leukemia as previous studies have shown these cells over-express the transferrin receptor." (PMID 27049725, 2016). "Here, we set out to assess the capacity of a novel doxorubicin - transferrin conjugate (DOX-TRF) to provoke apoptosis in human normal and leukemia cells through free radicals produced via a redox cycle of doxorubicin (DOX) when released from its conjugate." (PMID 26611752, 2016).
atherosclerosis (27 papers, 2011 to 2025). A disease characterized by the build-up of fatty material and calcium deposition in the arterial wall resulting in partial or complete occlusion of the arterial lumen. "TF is a key regulatory integral membrane protein on the surface of endothelial cells, implicated in atherosclerosis, and a major procoagulant for thrombus formation associated with endothelial dysregulation." (PMID 32707866, 2020). "TF expression by endothelium has been associated with the occurrence of thrombotic events in patients with a variety of clinical disorders including atherosclerosis." (PMID 28050226, 2016). "Although not in a fully conclusive manner, these promoter haplotypes were associated with TF expression levels and/or activity as well as to thrombotic and atherosclerosis risk in several studies." (PMID 25407675, 2014). "In conclusion, increased circulating MVs, in particular MMVs, EMVs, ErytMVs, and TF+ MVs, may contribute to atherosclerosis development and elevated atherothrombosis risk in patients with FH." (PMID 26925191, 2016). "Notably, the ratio of ferritin to transferrin/iron is causally related to atherosclerosis." (PMID 38474722, 2024). "Furthermore, significant inverse associations were found between the concentrations of transferrin and sTfR and the risk of dyslipidaemia in childhood, which may inversely relate to the risk of atherosclerosis and related cardiovascular disease in adulthood." (PMID 30755213, 2019). "Values of vitamin B12 (p = 0.000), triglycerides (p = 0.000), ferritin (p = 0.001), and transferrin (p = 0.000) were significantly higher in patients with atherosclerosis only." (PMID 36984554, 2023). "In atherosclerosis, abnormally up-regulated transferrin interacts with and potentiates thrombin/FXIIa and blocks AT’s inactivation effect on coagulation proteases by binding to AT, thus inducing hypercoagulability." (PMID 31811276, 2020). "We did not observe associations of the iron parameters, i.e., serum ferritin, serum iron, total-iron binding capacity (TIBC) and transferrin saturation (TS), with atherosclerosis." (PMID 26159428, 2015). "Hcy also played a significant role in inducing pro-inflammatory gene expression via TF-dependent signaling pathways in monocytes (MCs), leading to MC differentiation and MC-mediated inflammation, thus contributing to vascular inflammation and atherosclerosis." (PMID 40364032, 2025). "Furthermore, accumulating evidence of animal and clinical studies showed that TF and TFPI were closely associated with atherosclerosis and CAD." (PMID 34809656, 2021). "Reduced TF expression in macrophages may contribute to the observation that miR-181b overexpression in Apo E−/− mice protects from atherosclerosis." (PMID 32066445, 2020). "In conclusion, circulating levels of sST2 are associated with sP-selectin and monocyte TF expression in atherosclerosis but not with ischemic outcomes following infrainguinal angioplasty with stent implantation for PAD." (PMID 33415128, 2020). "Conclusion: sST2 is associated with soluble P-selectin and monocyte TF expression in atherosclerosis but not with ischemic outcomes following infrainguinal angioplasty with stent implantation for PAD." (PMID 33415128, 2020). "In the mouse model, transferrin overexpression aggravated atherosclerosis, whereas transferrin inhibition via shRNA knockdown or treatment with anti-transferrin antibody or designed peptides interfering with transferrin-thrombin/FXIIa interactions alleviated atherosclerosis." (PMID 31811276, 2020). "Lower transferrin (<2 g/L or 200 mg/dL) and higher ferritin (>300 μg/L serum ferritin in men and >200 μg/L in women, blood concentrations are recognized as biomarkers in inflammation and might even contribute to atherosclerosis and CVD." (PMID 38534331, 2024).
atherosclerosis (continued). "Therefore, the results from this study suggest that elevated iron or norepinephrine in the presence of transferrin may result in enhanced degradation of host tissues in patients with advanced atherosclerosis." (PMID 35543563, 2022). "Another study stated that non-transferrin-bound iron buildup at the cellular level and subsequent activation of macrophages may be the cause of atherosclerosis rather than elevated blood ferritin levels." (PMID 36289866, 2022). "Furthermore, in vitro IMs reacted to the alarmin IL-33 with an upregulation of TF via an NF-kB dependent pathway, a pathway probably active also in patients with atherosclerosis as monocyte-derived microvesicles positive for TF were correlated with IL-33 plasma levels." (PMID 30778349, 2019). "When patients with ulcerative colitis only and atherosclerosis only were compared, values of CRP (p = 0.000), transferrin saturation (p = 0.000), Ag PLT ADP (p = 0.000), leukocyte (p = 0.001) and fecal calprotectin (p = 0.000) were significantly higher in patients with ulcerative colitis only." (PMID 36984554, 2023). "The MIS was positively correlated with age, the number of hospitalizations, the presence of atherosclerosis, ferritin, IL-6, TNF-α, CRP and MIAS and inversely correlated with the BMI, albumin, prealbumin, hemoglobin, transferrin, creatinine and blood phosphorus." (PMID 33413177, 2021).